IL6 (interleukin 6)
Diseases named in the same sentence as IL6 in open-access papers (continued):
Sharing a sentence is not in itself a finding about the gene and the disease.
tumor (continued). "Several tumor cells including BrCa and PrCa cells as well as local cells of the TME such as adipocytes, macrophages, or osteoblasts are able to produce IL-6, IL-8, and IL-11." (PMID 34064859, 2021). "For example, macrophages, one of the most represented categories of cells in the tumor microenvironment, are recruited by different soluble factors produced by the tumor, such as CSF1 (colony stimulating factor 1) and IL6 (Interleukin-6)." (PMID 33926496, 2021). "To further confirm the effect of hypoxia on the cytokine expression of macrophages co-cultured with tumor cells, we knocked down the hypoxia modulator, HIF1α, in A549 cells and analyzed the expression of IL1A and IL6." (PMID 34362882, 2021). "Both IL6 and MCP-1, however, are proteins considered tumor promoting in the tumor setting, which stands in contrast to their role as acute immune regulators." (PMID 34771568, 2021). "Meanwhile, CAFs promote M2 polarization of macrophage via release of SDF-1, IL-6, and GM-CSF and overexpression of PAI-1, producing an immunosuppressive tumor ecological niche." (PMID 34868982, 2021). "The results revealed significant changes including the increased expression of tumorigenesis-related markers, such as CD133, Bmi-1, VEGF, MMP-3, IL-1β, IL-6, TNF-α, and MDR, as well as the apoptotic markers, Bax and Bcl-xL, in the REM134-driven tumor group." (PMID 34527741, 2021). "In head and neck carcinoma, other paracrine cytokines secreted by MSCs, including IL-6, IL-7, IL-8, and growth factors such as VEGF, have also been reported to be involved in the development of tumor drug resistance." (PMID 34095111, 2021). "Increasing immunogenic cell death of tumor cells; suppressing secretion of IFN-γ and inducing secretion of IL-6, TNF-α and TGF-β1 of tumor cells." (PMID 35002732, 2021). "Inflammatory cytokines like interleukin 6 (IL‐6) and tumour necrosis factor‐α (TNF‐α) released from tumour cells or the tumour microenvironment play a central pathophysiological role." (PMID 34636159, 2021). "TAMs preferentially secrete TGF-β to stimulate CSC-like properties by inducing EMT, while TAM-derived IL-6 induces CD44+ HCC stem cell expansion by activating STAT3, thus promoting tumor development through CSC growth." (PMID 34235155, 2021). "These tumor-infiltrating TAM are skewed toward CD163+ M2 phenotype under the action of the transcription factor, GATA3, and cytokines, including IL-4, IL-6, and IL-13, and promoted an immunosuppressive TME in EAC." (PMID 33995371, 2021). "We obtained four sensitive tumor samples and four resistant tumor samples and analyzed the expression levels of lncRNA MIAT, HMGB1, and IL6." (PMID 34094941, 2021). "This process prompts the release of pro-inflammatory cytokines, including IL-6, IL-12, IFN-γ and TNF-α, to create a delayed type hypersensitivity-like microenvironment that regulates prolonged anti-tumor adaptive responses." (PMID 34322780, 2021). "MSC niches respond to numerous signals generated by the tumor milieu, including TGF-β, IL-6, Cyclophilin B, HDGF, uPA/uPAR, MCP-1, VEGF and FGF2, which can act as chemoattractants for MSCs." (PMID 34359821, 2021). "A study by Lee and colleagues suggested that IL-10 inhibits the IL-6/STAT3 axis on MDSCs and weaken tumour progression." (PMID 34336101, 2021). "IL-6, gp130 and IL-6Rα were included to one DSS multivariate analysis that also included gender, age and tumor size in one Cox regression survival model." (PMID 32621022, 2021). "Our bioinformatic analysis revealed that IL6, IL6R, and IL6ST genes were significantly modulated in most of the cancers showing a tumor-dependent pattern." (PMID 34576335, 2021). "Targeting XBP1 inhibits the ability of pro-tumor cytokines, such as IL-6 and VEGFA, as well as promotes tumor growth and metastasis." (PMID 34667145, 2021).
tumor (continued). "Regarding this, interleukin (IL)-6, signaling through the signal transducer and activator of transcription 3 (STAT3), has shown to promote tube formation by tumor cells in vivo and in vitro by upregulating VE-Cadherin expression and MMP2 activity." (PMID 34359928, 2021). "Senescent BMR cells possess undetectable or decreased expression of several SASP proteins, such as IL-6, IL-8, GRO-1, and ICAM-1, which indicates that in contrast to senescent human somatic cells, they are unable to support tumor growth." (PMID 33034696, 2021). "MDSCs are actively drawn and activated in the tumors by various secretory products like PGE2, VEGF, GM-CSF, IL-6, TNF-α, IL-10, and IL-1β elaborated by TIICs, CAFs, and the tumor cells themselves." (PMID 33996630, 2021). "The secretion of IL-6, IL-8, and VEGF, and the activation of pro-inflammatory pathways seem to be the two canonical mechanisms by which MSCs respond to tumor cell-derived exosomes." (PMID 33738282, 2021). "ELISA analysis of IL‐6, TNF‐α and IFN‐γ in the serum of tumour‐bearing mice revealed a significant increase in their concentration after SEP treatment compared with NCs." (PMID 33289295, 2021). "Activated TLR2 or TLR4 in OSCC can trigger the production of IL-6 and other STAT3-activating factors that then act in autocrine fashion on the OSCC receptors, which is another major cell-intrinsic pro-tumor benefit of TLR activity." (PMID 35048056, 2021). "Many immunosuppressive factors produced by MDSCs, such as TGF-β, VEGF, IL-10, and IL-6, have been shown to induce EMT and stemness in various tumor cells." (PMID 35004667, 2021). "Here, we also demonstrated that propolis decreased the levels of proinflammatory mediators, including TNF-α, IL-1β, and IL-6, as well as NLRP3 inflammasome to improve the tumor inflammatory microenvironment." (PMID 33628847, 2021). "Exosomal HSP70 induces STAT3 phosphorylation and increases secretion of IL-6 and vascular endothelial growth factor (VEGF) in MDSCs, thus promoting tumor growth." (PMID 34917098, 2021). "When CCA cells were exposed to IL-6, a key inflammatory factor in the CCA tumor microenvironment, the level of the m6A modification was significantly elevated, accompanied by higher expression levels of phosphorylated STAT3 in the CCA cells exposed to IL-6." (PMID 34347395, 2021). "IL-6, through its ability to signal via the STAT3-JAK pathway, can enhance tumor cell survival, promote osteoblast and tumor cell production of RANKL and PTHrP to induce osteoclastogenesis, induce angiogenesis, and modulate immune cell function." (PMID 33805598, 2021). "Here we propose IL6 produced by ESCC tumors cells might induce the expression of several genes and downregulate a number of others in a juxtacrine fashion, but also induce the expression of genes involved in key cancer-associated pathways in the non-tumor surrounding tissue." (PMID 34422669, 2021). "The expressions of metastatic and EMT genes (SERPINE1, IL-6, and MMP-2) were induced in tumor cells by MSCs secreted leptin." (PMID 33472580, 2021). "By blocking the IL6 pathway, an HCC mouse model has demonstrated reduced tumor burden in the liver, presuming as a result of decreased chronic inflammation." (PMID 34080071, 2021). "Persistent hyperactivation of the IL-6/STAT3 signalling pathway also leads to angiogenesis, epithelial-mesenchymal transition and stemness in the tumour microenvironment." (PMID 34078370, 2021). "TAMs, Treg cells, neutrophils, and mast cells facilitate tumor sprouting angiogenesis by secreting proangiogenic molecules such as VEGF-A, IL-6, IL-8, and MMP-9 to support EC activation, proliferation, and survival." (PMID 34359588, 2021). "It has been shown that IL-6 and activated STAT-3 lead to increased formation of tumor spheres, which initiated tumor growth in vivo." (PMID 34204596, 2021).
tumor (continued). "As a result, the inhibition of the IL-6 signaling pathway controlled paraneoplastic inflammatory syndrome (PIS); however, the local recurrent tumor progressed." (PMID 34221525, 2021). "Inflammation often exists in the tumor microenvironment and is induced by inflammatory mediators such as TNF-α, IL-6, IL-1β." (PMID 33953676, 2021). "Additionally, tumor hypoxia with resulting acidosis is known to abrogate the function of surrounding immune cells via the induction of anti-immunogenic mediators (e.g., IL-1b, IL-8, IL-6, TNFα, and TGF-b) contributing to tumor cell escape of immunogenic control." (PMID 34831136, 2021). "Although both IL-6 and HGF activate STAT3 and induce ZEB2, they seem to play a different role in tumor progression." (PMID 34408135, 2021). "CAFs enhance the metastatic potential of human NSCLC cells through a IL6/STAT3 signaling pathway, which in turn promotes tumor angiogenesis through the upregulation of VEGF and bFGF." (PMID 34944848, 2021). "In vitro and in vivo evidence indicates that HS6ST2 is essential for vascular development and plays an important role in tumor angiogenesis due to its interactions with several angiogenic growth factors, including FGF2, VEGF, IL8, and IL6, among others." (PMID 34944958, 2021). "These components are controlled by 10 inputs from the tumour microenvironment (HGF, EGF, ECM stiffness, TGFB, IL6, DELTA, ROS, WNT and the ligands for RPTP and FAT4)." (PMID 34063110, 2021). "Other scholars believe that histamine secreted by mast cells can stimulate vascular endothelial cells to produce prostacyclin, which can mediate tumor cell necrosis and inhibit tumor cell metastasis together with TNF-a, IL-1, and IL-6 secreted by mast cells." (PMID 33946045, 2021). "A novel inhibitor of TLR-2, ortho vanillin, inhibited MMP-9, MMP-14, IL-6, and iNOS expression and decreased TLR-2-mediated pro-tumor M2 phenotype of brain resident macrophages." (PMID 34439380, 2021). "Further, constitutive TGFβ/IL‐6/STAT3 activation, tumour growth and lung metastasis in OS is perpetuated by paracrine activity from tumour extracellular vesicle–educated MSCs (TEMSCs) in mouse and human OS tissue samples." (PMID 33382511, 2021). "Meanwhile, secretion of IL6 and OSM by tumor stromal fibroblasts contributes to resistance of NSCLC cells to targeted therapies." (PMID 34944848, 2021). "At the tumor site, MSCs infiltrate into the stroma and produce bioactive molecules such as CCL5, IL-6, SDF-1 and TGFβ, which promote tumor growth and/or distant metastasis to secondary organs, such as the lungs." (PMID 34359821, 2021). "Neutralization of IL-6 or combination treatment of CD40 agonist and Flt3 ligand rescued cDC1 abundance, leading to the control of tumor outgrowth." (PMID 34290984, 2021). "When compared with the differentiated cells of triple-negative breast cancer cells, the stemness-bearing CD44+CD24− cell population has a preferentially higher activity in the IL-6/JAK/STAT3 pathway, leading to CSC proliferation and tumor growth." (PMID 34202411, 2021). "We further demonstrated that CD44 engagement by GPNMB activates in tumor cells the expression of several factors, including chemokines, e.g.: CXCL1, CXCL2, CCL2, CCL5, CCL7, cytokines: IL-6, IL-11, IL-33, and the IL-33 receptor: IL-1RL1, also named ST2." (PMID 34583655, 2021). "Upon stimulation with M-CSF, IL-6, GM-CSF, and VEGF by tumor cells, STAT signaling regulates Tregs, TAMs, and MDSCs, consequently exerting a tumor-promoting effect." (PMID 34527668, 2021). "The activation of TNF-α, IL-6, IL8, and VEGF triggers downstream signaling involved in promoting tumor growth and invasiveness to other parts of the body." (PMID 34096454, 2021). "Increased IL-6 in TME will trigger hyperactivation of downstream JAK/STAT3 signaling to drive proliferation, angiogenesis, and metastasis of tumor cells 13-16." (PMID 34093869, 2021).
tumor (continued). "Although tumor angiogenesis is mainly driven by vascular endothelial growth factor (VEGF), it is also affected by MMPs, interleukin (IL)-6, IL-8, and so on." (PMID 34307378, 2021). "M2 TAMs secrete pro-tumor factors (IL-4, IL-6, IL-10, IL-13, EGF, and VEGF), while tumor suppressor M1 TAMs express antitumor factors (IL-12, major histocompatibility complex (MHC) class II, and TNF-α)." (PMID 34341329, 2021). "On the other hand, autophagy is involved in the secretion of matrix metalloproteases (MMPs) and pro-migratory cytokine interleukin-6 (IL6), which promote tumor cell migration." (PMID 32985978, 2020). "Accordingly, our analysis of a subset of genes that had a significant Z score for similarity to proliferation of tumor cells predicted cell cycle progression through genes such as CDK4, HRAS, IL-4, CSF2, IFNG, IL-6 and STAT3." (PMID 33180876, 2020). "ICAM‐1 expressed on LSECs promoted secretion of IL‐6, prostaglandin E2, VEGF, and MMP2 by tumor cells, which in turn induced VEGFA and MMP2 secretion by HSCs." (PMID 33252863, 2020). "Taken as a whole, our study found at least three pathways, i.e., IL-6, CD86, and ICOSL, by which tumor B cells can contribute to Tfh activation and induce a potent microenvironment sustaining, in turn, FL cell growth." (PMID 33028033, 2020). "IL-6 can be produced by multiple cell types located within the TME, including tumor-infiltrating immune cells, stromal cells, and cancer cells themselves." (PMID 32855767, 2020). "The researchers further showed that inhibiting the recruitment of TAMs decreased pSTAT3 expression and IL-6 secretion within the TME, leading to delayed IBC tumor formation and reduced skin invasion and local recurrence." (PMID 32883032, 2020). "CAFs remodel tumor vasculature through secretion of VEGF, FGF and IL-6, and ECM, through secretion of matrix metalloproteinases (MMPs) and ECM proteins." (PMID 32499779, 2020). "IL-1β, while promoting increased synthesis of IL-2, IL-6, and TNF-α, also acts as a tumor growth promoting molecule in conditions of chronic inflammation." (PMID 33718121, 2020). "We previously identified several key factors in mediating CAFs’ tumor-promoting properties in GC, including HGF, Lumican and IL-6." (PMID 31659258, 2020). "It was observed that tea polyphenols (0.1% in water for 42 days) inhibited the formation of tumor through down-regulating the expression of COX-2, TNF-α, IL-6, β-catenin, and C-myc and up-regulating the expression of IL-4 and IL-10." (PMID 32410986, 2020). "The increased secretion of IL-6 and GCSF by STK24-knockdown tumor cells and the enhanced tumor growth were observed in the current study." (PMID 31892988, 2020). "Increased production of G-CSF, GM-CSF, and IL-6 in culture supernatants and enhanced MDSC production in tumor-bearing mice were observed in AdIL-17A-transduced E0771 cells compared to Addl control counterparts." (PMID 32770025, 2020). "Macrophages produce many factors that contribute to tumor growth, including VEGF, IL-1, IL-6, nuclear factor-kappa B (NF-κB), tumor necrosis factor-alpha (TNF-α) and macrophage colony-stimulating factor (M-CSF)." (PMID 32774171, 2020). "To study if stromal IL6 was activating the canonical JAK/STAT pathway in the tumor cells, we next evaluated the activation of STAT3 by treating with IL6." (PMID 33177492, 2020). "For example, upon contact with tumor cells, macrophages become activated, thus releasing inflammatory cytokines and chemokines such as TNF, IL-1, IL-6, IL-8, and IL-12." (PMID 32784928, 2020). "Previous study has shown an increased serum IL-6 concentration as one of the cachexic phenotype, indicating the successful induction of CCX in C-26 tumor bearing mice." (PMID 32425814, 2020).
tumor (continued). "Increased autocrine production of the growth factors, including interleukin (IL)-1, IL-4, IL-6, and IL-8, has been observed in MDR cancer cells, compared to drug-sensitive tumor cells." (PMID 32370233, 2020). "CAFs from hepatic cancer attract monocytes to the tumor microenvironment by CXCL12 and induce their differentiation into MDSCs through IL-6-mediated STAT3 activation." (PMID 32793192, 2020). "The shortest width and longest diameter of the transplanted tumors in the nude mice were measured every 3 days.TLR4, IL-6,iNOS, IL-8,COX-2, MIP-3α, TGF-β1 and VEGF expression levels in the transplanted tumor tissue were detected by immunohistochemistry." (PMID 32095158, 2020). "Inflammation occurs in the tumor microenvironment, which in turn accumulates a large number of cytokines, chemical mediators and enzymes, such as TNF-a, IL-6, VEGF, iNOS, Cox-2, and MMP-9, for mediating inflammation and driving its malignant transformation." (PMID 31343435, 2020). "In this same line, inflammatory factors in the tumor microenvironment, including TGF-β, IL-6, IL-1β, IL-8, and others can induce EMT." (PMID 32545405, 2020). "In contrast, CD200 overexpression in CD200 transgenic mice was found to increase tumor-induced IFN-γ and decrease inflammatory cytokine, TNF-α, and IL-6 expression." (PMID 32635224, 2020). "Collectively, these results indicate the importance of HDAC activation and IL-6 signaling pathways in regulating immunosuppression and myeloid cell recruitment to CRC tumor tissues." (PMID 31941522, 2020). "By specifically targeting microglia, using propentofylline which blocks secretion of IL-1β, IL-6 and TNF-α, tumor growth was found to regress." (PMID 32765498, 2020). "IL-6, secreted by the myeloid cells, activates STAT3, which then upregulates cyclins D1, D2, and B as well as MYC to promote tumor cell proliferation." (PMID 33143283, 2020). "Upregulation of PD-L1 expression in tumor cells is triggered by activation of the cGAS/STING pathway, followed by IFNα/β, or IFN-γ by CD8+ T cells, or the IL-6-mediated STAT-IRF1 pathway." (PMID 33297519, 2020). "IL-6 and IL-10 were detected in HNSCC cell lines, primary HNSCC cells, as well as tumor-infiltrating immune cells." (PMID 33042814, 2020). "Similar to NK cells, macrophages play an important role in innate host defense and in killing tumor cells by producing reactive oxygen/nitrogen species and pro-inflammatory cytokines such as tumor necrosis factor-alpha (TNF-α) and interleukin 6 (IL-6)." (PMID 33374978, 2020). "Tumor invasion and metastasis augmented by tumor necrosis factor (TNF) and IL-6 were identified as mast cell chemo-attractants." (PMID 32260363, 2020). "The inhibitory effect of XYS was accompanied by downregulated expression of TGF-β, IL-6, MMP-9 and VEGF in spleen tumours, as well as suppression of VEGF and CD31 proteins in hepatic metastatic tissue." (PMID 33152259, 2020). "MDSC present in the TME adopt an immunosuppressive phenotype, enhance tumor cell stemness, angiogenesis, and EMT, through IL-6." (PMID 33142779, 2020). "CCL5 increases tumor growth by activating STAT5 and cyclin D1 pathways, enhanced tumor invasion and synergizes with IL-6." (PMID 32630699, 2020). "These cytokines further stimulate macrophages to produce large amounts of IL-6, IL-1 and TNF-α to enhance the toxicity of macrophages to tumor cells." (PMID 32161718, 2020). "Mean (±SD) total tumor volume (TTV) was 13.6 (±6.2) mm3 (median 16.2, IQR: 9.3–17.3) in the IL-6 KO, while it was 21.9 (±6.6) mm3 (median 18.1, IQR: 16.2–28.3) in the WT subgroup." (PMID 32867390, 2020). "After a series of validation experiments for the concerned genes, it was found that IL6, GM‐CSF (CSF2), IL11, CCL3, S100A8 and S100A9 were significantly decreased in the gut tumours of ApcMin/+ TLR4−/− mice compared with ApcMin/+ WT mice." (PMID 31650683, 2020).